RELA (RELA proto-oncogene, NF-kB subunit)
Diseases named in the same sentence as RELA in open-access papers (continued):
Sharing a sentence is not in itself a finding about the gene and the disease.
tumor (continued). "RelA has been reported to upregulate PD-L1 in tumour cells in response to TNF-α and LPS stimulation or by cooperation with RB phosphorylation." (PMID 35177112, 2022). "Canonical NFκB signaling via p65/RELA is known to promote carcinogenesis, enhance tumor cell survival and tumor progression, promote the development of metastatic disease, and induce resistance to standard of care chemotherapy regimens in TNBC37–42." (PMID 35177654, 2022). "Initial studies demonstrated that phosphorylation of this site results in a pro-apoptotic form of RelA in response to induction of the ARF tumour suppressor or treatment with the chemotherapeutic drug cisplatin." (PMID 36240065, 2022). "NGS analysis and subsequent qRT-PCR analysis suggested that blocking IKK potentiates EGFR inhibition at least partially though the suppression of NF-κB/RELA-dependent transcription of tumorigenic genes and induction of tumor suppressors." (PMID 36358633, 2022). "Gene expression analysis revealed that several NF-κB/RELA targets were suppressed, and a couple of tumor suppressor genes were induced by the drug combination." (PMID 36358633, 2022). "For example, RelA promotes cell proliferation while RelB supports viability of tumour-initiating cells, and both act to promote spheroid formation." (PMID 35194062, 2022). "The Myd88L252P tumor transcriptomic signature identified both proliferation and canonical NF-κB p65/RelA activation." (PMID 34017329, 2021). "The NF-κB signaling pathway comprises a family of five transcription factor subunits (p65/RelA, c-Rel, RelB, p50/NF-κB1, and p52/NF-κB2), which are key regulators of tumor cell growth, proliferation, metastasis, and chemotherapy resistance." (PMID 34976812, 2021). "MAEL can be involved in ESCC progression by regulation of AKT1/RelA/IL8 signaling to recruit Myeloid-Derived Suppressor Cells (MDSCs) to tumor sites." (PMID 33902648, 2021). "Recently, a genome-wide CRISPR approach revealed that ablation of the RNA helicase Dhx37 in murine T cells improved tumor clearance by increasing RelA activity." (PMID 33572260, 2021). "NF-KB pathway was regulated by Phosphorylated RELA which is related to the course of tumor, and inflammation-related diseases." (PMID 33767987, 2021). "Overall, 9 of 10 tumours with the RELA+ signature possessed the ZFTA‐RELA fusion as detected by next‐generation sequencing (p = 0.005)." (PMID 34314101, 2021). "In this study, we found that PM possesses an adequate therapeutic effect on CRC, primarily by inhibiting RelA expression and NF-κB pathway from promoting tumor apoptosis." (PMID 34867383, 2021). "NF-κB is a crucial transcription factor in the inflammatory tumor microenvironment, and RelA/P65 is center to the activation of Wnt signaling by NF-κB, which is one of the center mechanisms of tumor cell initiation in CRC." (PMID 34867383, 2021). "The results revealed two main clusters: cluster 1, which included nine tumours with high expression of RELA+ signature genes; and cluster 2, which contained six tumours without the expression of signature genes." (PMID 34314101, 2021). "Next, we investigated the expression of CD82 and ROS1 mRNA by real-time qPCR in vector control and RelA/p65KD A549 and H1437 cancer cells grown as tumour xenografts in mice." (PMID 34503110, 2021). "We show here that NF-κB RelA/p65 is required for the tumour growth of human NSCLC cells grown in vivo as xenografts in immune-compromised mice." (PMID 34503110, 2021). "The majority of supratentorial tumours contain oncogenic fusions between the genes C11orf95 and RELA (C11orf95–RELA) or YAP1 (YAP1‐MAMLD1)." (PMID 34314101, 2021). "Tumours from the RELA+ cluster exhibited high RELA gene expression, with the exception of one sample that showed low RELA expression." (PMID 34314101, 2021). "The relative transcript levels of RelA and IKKβ were significantly increased in the tumor-bearing vehicle-treated group compared to the tumor-free vehicle-treated group." (PMID 33718372, 2021).
tumor (continued). "A549 and H1437 NSCLC cell lines were used to generate RelA/p65-compromised derivatives and investigate its impact on tumour growth and its mechanism(s) of action." (PMID 34503110, 2021). "From a clinical perspective, it is crucial to identify RELA fusion‐positive tumours, as initial data have suggested a poor prognosis for patients." (PMID 34314101, 2021). "As expected, WFA treatment in both tumor-free and tumor-bearing animals led to a significant reduction in relative transcript levels of RelA and IKKβ compared to their vehicle-treated controls." (PMID 33718372, 2021). "NFKB1 and RELA are biomarkers in NF-κB pathway, which has been reported to regulate tumor invasiveness." (PMID 34486492, 2021). "Knockdown of LMP1 leads to inactivation of the RelA/p65-HK-2 signaling pathway, thereby inhibiting tumor development." (PMID 35083281, 2021). "Canonical NF-κB signalling components such as the IKKβ kinase and RelA/p65 have been shown to act as tumour promoters in several models of NSCLC." (PMID 34503110, 2021). "The RelA (p65) nuclear NF-κB subunit contributes to tumor cell survival by inducing the expression of a variety of antiapoptotic genes." (PMID 32713851, 2020). "The statistical analytic data indicated that the mRNA levels of RelA and RelB in tumor tissues were higher than their levels in normal breast tissues, particularly the difference in RelB levels appeared to be highly associated with BCa progression." (PMID 32807176, 2020). "FOXO1, CEBPB, and RELA mRNA expression in stage IV tumor tissues was significantly higher than that in stage II tumor tissues, indicating that the signaling molecule signatures are closely correlated with the tumor stage." (PMID 31395078, 2019). "While RELA overexpression promoted tumor growth and vice-versa, RELB overexpression decreased tumor growth." (PMID 31602271, 2019). "To investigate the role of TNF-α, we analyzed the association of the level of NF-κB p50 transcripts with the methylation status of the NFKB1 and the RELA genes in tumor tissues depending on the expression of TNF-α." (PMID 31382678, 2019). "Canonical NF-κB signaling through p65/RelA can be activated in response to inflammatory chemokines and cytokines in the tumor microenvironment." (PMID 31443240, 2019). "In contrast, we were not able to show a tumor cell intrinsic function of the chemokine but confirmed through a genome-wide unbiased approach that NF-κB/RelA regulates the expression of CX3CL1 in PDAC tumor cells." (PMID 31561620, 2019). "FISH analysis of tumor from patient #21 showed a rearrangement both for RELA and C11orf95 genes in concordance with nuclear p65‐RelA expression." (PMID 30325077, 2019). "In summary, this work suggested a RelA/CXCL1/CXCR2 axis as a major guardian against PDAC tumor development." (PMID 31561620, 2019). "Our work provides evidences to demonstrate the direct binding of HOXA9 on RELA promoter and deepen the understanding of HOXA-RELA regulator axis, which highlights the tumor-suppressive role of HOXA9 in cSCC." (PMID 31683603, 2019). "The microRNA-520/373 family functions as a tumor suppressor in ER-negative breast cancer by targeting NF-κB p65/RelA and also TGFβ signaling by directly suppressing TGFBR2 and several Smad-dependent metastasis-promoting genes." (PMID 31557902, 2019). "The oncogenic or tumor suppressor functions of RelA, c-Rel, and RelB can be highly context-specific, showing variation not only in different cell types but also depending on the stage of malignant transformation." (PMID 31277415, 2019).
tumor (continued). "Taken together, these animal data suggest that p68 enhances primary tumor growth, leads to upregulation of RelA and subsequent activation of oncogenic NF-κB signaling axis and corroborates the correlation between p68 and expression of NF-κB target genes." (PMID 31351496, 2019). "In mice, the RELA fusion protein drives tumor formation in forebrain-derived neural stem cells (NSCs) in allograft or the RCAS/tv-a system models." (PMID 31477715, 2019). "In the present study, we identified that XAF1 attenuates NF-κB-mediated transcription of tumor-promoting genes by facilitating IRF-1 repression of p65/RelA-mediated transcription." (PMID 30042418, 2018). "The clinicopathological parameters such as age, gender, tumor size, stage and grade were assessed with the localization of the RelA/p50 heterodimers." (PMID 30225173, 2018). "Canonical NF-κB can also inhibit tumor growth by inducing the expression of tumor suppressors such as Bach2 induced in B-cells by c-Rel or RelA suggesting a tumor suppressive function of c-Rel in B-cell lymphoma." (PMID 29601548, 2018). "Generally, RelA activity plays a tumour-supportive role and functions as an independent prognostic factor in NSCLC." (PMID 29983639, 2018). "In agreement with this proapoptotic function of NF-κB, we found that interference with RelA/p65 prevented trabectedin-dependent apoptosis in premature senescent tumor cells." (PMID 29731994, 2018). "The NF-κB subunits RelA/p65, p52 and RelB are highly expressed and chronically activated in almost 80% of the tumours and thought to fosters NF-kB anti-apoptotic and pro-proliferative activities as well as contribute to all the remaining hallmarks of cancer." (PMID 29673148, 2018). "An increased NF-κB RELA signaling was likewise observed in tumor-initiating stem-like cells in human prostate cancer." (PMID 29673141, 2018). "In tumor cells, the inhibiting effect of RelA knock-down seems to be much more pronounced compared to HEK cells." (PMID 30061500, 2018). "It was reported that high nuclear abundance of RelA (by immunohistochemical analysis) in surgically resected specimens was related to tumor progression and predictable for a poor patient survival." (PMID 28350359, 2017). "Depletion of JUN and JUNB or RELA in tumor cells blocked the cooperative induction of MMP9 by the cytokines." (PMID 28423685, 2017). "Several members of the canonical NF-κB pathway were in the top list, including RELA, NFKB1, CHUK, IKBKB, IKBKG, and REL, indicating that the canonical NF-κB pathway was closely associated with immune-related DEGs in tumour serum-cultured DCs." (PMID 28350008, 2017). "NFKB1-positive tumors were more likely to be found in elder age group (P = 0.052), but RELA-positive tumor are strongly correlated with N stage (P = 0.042)." (PMID 26801246, 2016). "DEN was, therefore, administered to 15-day-old WT and RelA T505A mice and tumour growth was evaluated after 30 weeks." (PMID 26853469, 2016). "Analysis of these tumours revealed that both homozygous and heterozygous RelA T505A mice had significantly higher numbers of visible liver tumours." (PMID 26853469, 2016). "NFκB transcription factors are homodimers or heterodimers of NFκB1 (p50), NFκB2 (p52), RelA (p65), RelB, or cREL, and have been widely reported to participate in tumor initiation, cell proliferation, apoptosis, chemoresistance, and the EMT." (PMID 26942699, 2016). "In tumor tissues, the nuclear translocation of RelA/p65 was also increased in both tumor cells and stromal cells of the HAI-1-deficient intestine." (PMID 27612426, 2016). "In neuronal cells, likewise in tumor cells, gene targeting by p50/RelA is finely regulated by post-transcriptional modification of RelA subunit, such as phosphorylation and acetylation." (PMID 26042083, 2015). "The molecular determinants governing opposing tumor promoting and inhibitory activities of RelA is unclear." (PMID 26460486, 2015).
tumor (continued). "Since RelA is widely expressed, we first screened TCGA samples based on tumor purity derived using the ESTIMATE procedure." (PMID 26460486, 2015). "Since RelB expression has been found to be regulated by both the canonical as well as the alternative NF-κB pathways, we next sought to examine a possible correlation between RelA expression in tumor or stroma compartments, and RelB expression in tumor cells." (PMID 26147201, 2015). "In this study, RelA expression was separately reported in the nuclear and cytoplasmic compartments of tumor cells, qualitatively determined by immunohistochemistry and ordinary microscopy." (PMID 26460486, 2015). "These analyses identified that, although expression levels of RelA in tumor areas were quite low, they were increased in tumors with high levels of inflammatory infiltration." (PMID 26147201, 2015). "In the meantime, significantly more RelA is expressed in tumor tissues than that in paracancerous tissues, while significantly less IκB is expressed." (PMID 25225511, 2014). "Our data clearly demonstrated that both YY1 and RelA are important regulators of MM tumor growth in the xenograft models." (PMID 23874387, 2013). "To determine if LTβ upregulation is associated with activation of NF-κB signaling in the FL-N/35 tumors, we first investigated RelA (p65) localization in livers of tumor-bearing animals." (PMID 23555249, 2013). "In line with its role in survival of MM cells, similar to YY1-depletion, depletion of RelA also has completely impaired MM tumor growth in xenograft model." (PMID 23874387, 2013). "One breast (MDA-MB-231) and two ovarian (OVCAR10, OVCAR5) tumor cell lines were cultured subjected to ChIP with an antibody (Ab) to RelA/p65." (PMID 22952718, 2012). "In contrast, decreases in NKRF, increases in p-RelA and mot-2, and increases in cell colony numbers in soft agar and tumor volumes in nude mice induced by 1.0 μM arsenite were more pronounced than those caused by 0.5 or 2.0 μM arsenite." (PMID 20199942, 2010). "There were 748 NF-κB targets predicted and individually annotated for RELA, NFκB1 or cREL regulation, and a prevalence of RELA related genes was observed in over-expressed clusters in a tumor subset." (PMID 18334025, 2008). "Overexpression of cytoplasmic and/or nuclear RelA in tumour tissue has been previously observed in larger study cohorts of gastric, prostate, endometrial, hepatocellular and oral as well as cervical carcinoma." (PMID 17622249, 2007). "Concerning tumour stage and nodal status, a strong trend towards higher cytoplasmic and nuclear RelA expression levels was observed for locally more advanced and nodal-positive tumours." (PMID 17622249, 2007). "For nuclear RelA, in this subgroup, median survival of patients with positivity in the tumour was reduced to 10.1 months while the median survival time was not reached in the remaining patients without nuclear RelA overexpression (P=0.023)." (PMID 17622249, 2007). "Mesenchymal cells of desmoplastic tumour stroma exhibited nuclear RelA expression in a minority of cells as well." (PMID 17622249, 2007). "Surprisingly, our results demonstrated that over-expression of relA determines a considerable reduction of the tumorigenic ability in nude mice as indicated by the tumour take and the median time of tumour appearance." (PMID 11747334, 2001). "Assembly of the RelA/Dnmt1 complex at the BRMS1 promoter region results in gene hypermethylation and transcriptional repression, which are associated with a dramatic increase in tumor metastasis." (PMID 40562870, 2025).
tumor (continued). "This revealed clear hypertranscription (Tumor >> Normal RNAPII) for the RELA-driven tumor." (PMID 39946483, 2025). "Consequently, CSK23 depletion increased cell death rate and inhibited the migratory capability of tumor cells in confining spaces, while RelA overexpression restored the survival and migration of CSK23-depleted cells in confinement." (PMID 41390768, 2025). "Taken together, these results suggested that RELA acts as a tumor suppressor in HCC progression." (PMID 40919676, 2025). "Indeed, increased expression of RELA mRNA, encoding p65 protein, and the activation of TNF-α-mediated NF-κB signaling are observed in GBM-formed tumor masses." (PMID 40288646, 2025). "Clinically, our data suggest that RELA dysfunction occurs in a substantial proportion of HCC cases, with low RELA expression showing a significant association with larger tumor size." (PMID 40919676, 2025). "RELA plays a critical role as a transcriptional component in the NF‐κB pathway, promoting the upregulation of proinflammatory and carcinogenic molecules that contribute to tumor development and treatment resistance." (PMID 39821576, 2025). "Notably, nuclear RelA levels showed a strong positive correlation with ALDH1B1 expression in confined tumor cells." (PMID 41390768, 2025). "Currently, there are limited reports on the tumor-related effects of RELA and CTCF." (PMID 41048344, 2025). "The RELA expression level was significantly (p < 0.01) higher in the normal tissue than in the tumor tissue in UCEC patients, whereas it was significantly (either p < 0.01 or p < 0.001) higher in the tumor than the normal tissue in COAD, STAD, and GBM patients." (PMID 38542508, 2024). "Mechanistically, the intercellular mtDNA transfer activates the mitochondrial respiratory chain to induce the ROS-driven RelA nuclear translocation in CECs, thereby transcriptionally regulating TGFβ1 expression and promoting tumor progression via the TGFβ/Smad pathway." (PMID 38688896, 2024). "Moreover, RELA is hyperactive in 50–70% of PDAC tumours and contributes to both cancer progression and resistance to chemotherapy." (PMID 39110005, 2024). "The effect of RelA/p65 Ser536 phosphorylation on tumor metastasis was further explored." (PMID 39498383, 2024). "Additionally, rosmarinic acid complements the action by targeting MAPK1, IKBKB, JUN, and RELA to synergistically inhibit the proliferation of tumor cells and induce apoptosis." (PMID 39840098, 2024). "In summary, the inhibition of MMP9 and RELA might explain the tumor growth reduction and prolonged survival by a combination of reduced matrix degradation, lower invasion and reduced growth factor release (i.e. VEGF)." (PMID 37963919, 2023). "Intriguingly, we observed that RelA-MUT GSC11, a recurrent PDX model, loses MES expression and gains PN expression, suggesting that the MES transition is linked to epigenetic alterations as seen in other tumor types." (PMID 37461511, 2023). "This is likely due to RELA partly constituting the canonical NF-κB signaling pathway, which can be activated by multiple stimuli and could contribute to its dysregulation in a tumor microenvironment." (PMID 37175530, 2023).